GSK3B (glycogen synthase kinase 3 beta)
Diseases named in the same sentence as GSK3B in open-access papers (continued):
Sharing a sentence is not in itself a finding about the gene and the disease.
infection (continued). "Infection with Ad-Akt increased expression of phosphorylated Akt, Akt and phosphorylated GSK-3β protein, consistent with previous results demonstrating that GSK-3β acts as a substrate of Akt." (PMID 21439087, 2011). "Mechanistically, C. atrati and 4′HAP activated GSK3β, destabilized HIF-1α, and curtailed parasite fitness; pharmacologic GSK3β inhibition restored parasite growth, whereas HIF-1α depletion further reduced survival, highlighting the GSK3β/HIF-1α axis as a host pathway that constrains infection." (PMID 41509906, 2026). "After 24 h infection with equivalent viral titres of each GSK3 adenovirus the levels of GSK3α were increased 5-6-fold and the levels of GSK3β doubled (n.b. the recombinant GSK3β has a Myc tag which means it has a slightly higher molecular mass than endogenous GSK3β)." (PMID 38479223, 2024). "Infection of HAEC HA549 with Mycobacerium bovis Bacillus Calmette-Guerin (BCG), a Gram-positive bacillus, or stimulation with LPS from unspecified origin (UO) exhibited TLR2/6 signaling activation and Wnt/β-catenin activity inhibition due to an increase in Axin and GSK3β expression." (PMID 34017345, 2021). "However, the β-catenin expression level in GSK-3β knockdown cells was 1.9-fold of that in HUVECs without treatment under infection conditions (P = 0.0002)." (PMID 25385175, 2015). "Furthermore, the monomer form of GSK-3β from infected cells was more sensitive to both BIO and BIOder treatment, suggesting that GSK-3β alone is more accessible to the inhibitors and is in greater abundance following infection." (PMID 22496857, 2012). "In a murine model of lung injury by P. aeruginosa non-lethal infection, therapeutic interventions included AMPK activator metformin or GSK-3β inhibitor Tideglusib for 96 h." (PMID 37438806, 2023). "Moreover, on the same brain slice absence of Gsk3β expression was only noted in virus infected neurons (infected with AAV spCas9 + AAV Gsk3sgRNA/GFP), while neurons outside of the infection area expressed Gsk3β." (PMID 29706865, 2018). "To test whether GSK-3β inhibition influenced intracellular GAS replication, we estimated the amount of remaining bacteria in the wild type GAS-infected RAW264.7 cells with or without LiCl at 1.5 h or 18 h post-infection using a plate counting assay." (PMID 30926881, 2019). "Notably, a high viral load of DENV infection alone, as demonstrated by plaque assays (P<0.001), significantly (P<0.001) induced IL-10 production in a multiplicity of infection (MOI)-dependent manner, although phosphorylation of PKB at Ser473 and GSK-3β at Ser9 was not increased." (PMID 25412261, 2014).
neurological diseases (50 papers, 2012 to 2026). "P-AKT is a major anti-apoptotic kinase, so AKT/GSK3β signaling abnormalities are associated with many neurological diseases." (PMID 32333225, 2020). "Activation and inflammatory responses of SH-SY5Y cells are usually associated with the PI3K/mTOR/GSK3β signaling pathways, which in turn trigger a range of neurological diseases, such as hypothalamic inflammation, AD, and PD." (PMID 32832542, 2020). "GSK3β serine/threonine kinase has been implicated in many diseases and disorders including metabolic, immune and neurological disorders, aging and cancer." (PMID 29724995, 2018). "As a signaling pathway which regulates cell survival, the Akt/GSK3β pathway has been implicated in many diseases including nervous system diseases, such as global and focal cerebral ischemia, traumatic brain injury, and spinal cord injury." (PMID 24763696, 2014). "GSK-3β also has a role in neuronal development and survival and has been implicated in a number of neurological disorders." (PMID 21843906, 2012). "Future studies, as well as more evaluations, will be needed to test whether GSK3β inhibitors may be promising candidates for treatment of human neurological disorders due to loss or dysfunction of WWOX." (PMID 32000863, 2020). "Here we demonstrate how changes in GSK-3β activity and/or levels regulate the production and subsequent secretion of fractalkine, a chemokine involved in the immune response that has been linked to AD and to other different neurological disorders." (PMID 27832289, 2017). "As more is learned about differential regulations and actions of GSK3α and GSK3β, it may be possible to devise more specific therapeutic interventions for a number of neurological disorders associated with GSK3 signaling." (PMID 29234272, 2017). "Glycogen synthase kinase-3 beta (GSK-3β) is a vital protein kinase known to be upregulated in various neurological disorders, including chronic progressive MS." (PMID 38732190, 2024). "GSK-3β is involved in almost all aspects of brain functions, such as neuronal morphology, synapse formation, neuroinflammation, and neurological disorders." (PMID 38107562, 2023). "Individually or in concert, DFO's chelation of free iron, its activation of the HIF‐1α pathway, and its inhibition of GSK‐3β likely contribute to its impact in neurologic disease states." (PMID 31960628, 2020). "PP2A, GSK3β and Tau reside together in a complex, which facilitates their interaction and (dys)-function as has been reported for several neurological disorders." (PMID 30781361, 2019). "This has major implications for numerous neurological diseases; for example, overactive GSK3β and dysregulation of PP2A were found to be clearly associated with several neuropathologies (see introduction)." (PMID 30781361, 2019). "We recently reported that insulin-dependent inhibition of GSK3β, a kinase with a growing list of neurologic disease links, phosphorylates dynein and regulates its interactions with Ndel1 and APC." (PMID 29404402, 2018). "The GSK-3β isoform is more abundant in the nervous system and has focused more attention on the involvement of GSK-3β in neurological diseases." (PMID 29082245, 2017). "In the brain, both GSK3α and GSK3β are expressed, and disruption of GSK3 signaling has been implicated in a number of neurological diseases, such as schizophrenia, major depression, bipolar disorder, and neurodegenerative diseases." (PMID 29234272, 2017). "The role of GSK3β in mediating peripheral and central nervous system inflammation in a multitude of neurological disorders has been extensively studied." (PMID 25906473, 2015). "A number of studies have confirmed that the activation of the Akt/GSK3β pathway attenuates apoptosis and correlates with regulation of Bcl-2, Bax and caspase 3 to mediate cell survival in many neurological diseases." (PMID 24763696, 2014).
neurological diseases (continued). "There has been much interest in inhibiting GSK-3β for the treatment of Alzheimer's disease, and other neurological disorders, due to its ability to phosphorylate the microtubule associated Tau protein as well as influence inflammation." (PMID 22496857, 2012). "These small chemical molecules are inhibitors of GSK-3β, which is known to have important implications in inflammation and neurological disease." (PMID 22496857, 2012). "These alterations might be relevant in the context of neurological diseases in which the activity of GSK-3β is dysregulated." (PMID 37481766, 2023). "Indeed, chemical modulators for Cdc42, LIMK1, and GSK3β are currently available and several FDA-approved GSK3β inhibitors are already being used in the treatment of neurological diseases." (PMID 31134199, 2019). "In this study, we demonstrate how the amount of both membrane-anchored and soluble fractalkine depends on GSK-3β activity/levels, a kinase which has been proposed as a key element in AD pathology and with many other implications in other neurological disorders as well." (PMID 27832289, 2017). "This work provides for the first time a mechanism linking GSK-3β and fractalkine both in vitro and in vivo, with important implications for neurological disorders and especially for AD, in which levels of this chemokine might be useful as a diagnostic tool." (PMID 27832289, 2017). "Additional studies are necessary to reveal the exact roles and mechanisms of GSK3β in neural activity, which may help us to understand the potential etiology of some neurological disorders in which GSK3β activity is involved." (PMID 23658842, 2013). "Therefore, GSK‐3β is considered a therapeutic target for a variety of nervous system diseases." (PMID 32108985, 2020). "Not surprisingly dysregulation of GSK-3β activity either in the early development or in the adulthood may predispose to neuropsychiatric and neurological disorders." (PMID 31191636, 2019). "Recently, with the deepening of research on the relationship between GSK‐3β and the occurrence and development of various diseases, the research on targeting GSK‐3β in treating various nervous system diseases has become an important topic." (PMID 39129397, 2024). "In the next section, we summarize the regulatory mechanisms of GSK-3β action, the physiopathological functions of GSK-3β in the brain, the current development of GSK-3β inhibitors, and treatment of brain and neurological diseases." (PMID 38107562, 2023). "GSK-3β, a versatile serine threonine kinase, has been identified to play a pivotal role in mediating the proliferation and differentiation of NSC during embryonic development and neurological diseases." (PMID 35186189, 2022). "We report, here, our results of the treatment of control and sporadic ALS lymphoblasts with Tideglusib, an in-house designed non-ATP competitive GSK-3β inhibitor, that have shown good safety and tolerability in patients with different neurological diseases." (PMID 34445680, 2021). "Therefore, miR‐21 has an ability to regulate PI3K/AKT/GSK‐3β signalling, and activation of AKT/GSK‐3β plays a protective role in many neurological diseases." (PMID 32108985, 2020). "Thus, IGF-1 is a promising therapeutic option for the treatment of various neurological disorders through regulation of multiple neuroprotective signaling pathways, including Ras/Erk1/2, PI3K/MAPK/Akt/mTOR, Ca2+/CaMK II and IV, CREB, C/EBPβ, and GSK3B/NF-kB/NLRP3." (PMID 36691085, 2023).
psychiatric disorder (48 papers, 2008 to 2026). A disorder characterized by behavioral and/or psychological abnormalities, often accompanied by physical symptoms. "Glycogen Synthase Kinase 3-beta (GSK3β) is a kinase linked to tau phosphorylation and associated with psychiatric disease susceptibility that functions as a major point of integration for critical neuronal signalling pathways." (PMID 35611312, 2022). "One reason that GSK3β is linked to psychiatric diseases is that GSK3 is a target of lithium, a mood stabilizer used to treat mental diseases." (PMID 30285728, 2018). "While GSK3α is usually important in neurodegenerative and psychiatric diseases GSK3β is fundamental in the inflammatory response caused by bacterial components." (PMID 26200352, 2015). "Altogether, these findings indicate that GSK3β inhibition of the Kv7.2 channel may cause hyperexcitability in psychiatric diseases." (PMID 35457230, 2022). "In addition, Akt/GSK3β signaling is associated with the treatment responses of therapeutic agents of mental illness." (PMID 31275123, 2019). "It is now shown that lithium, a mood stabilizer for mental illnesses, inhibits GSK-3β activity both directly and indirectly." (PMID 39200803, 2024). "The aberrant activation of GSK-3β related to neurological and psychiatric disorders characterized developmental abnormalities and altered neurocircuitry stability." (PMID 36414713, 2024). "GSK3β inhibition is not only an effective therapy for several neurological and psychiatric disorders, but is also beneficial for addictive drug-induced neurotoxicity." (PMID 36949769, 2023). "Despite these concerns, lithium salts, which include GSK3β as one of their targets, have been used for decades to treat psychiatric disorders, demonstrating the feasibility of long-term GSK3β inhibition at appropriate doses." (PMID 36669494, 2023). "GSK3β is one of the main substrates of Akt that has been studied extensively in psychiatric diseases." (PMID 35757972, 2022). "Lithium chloride (LiCl), an inhibitor of GSK3β that promotes GSK3β phosphorylation and inactivation, has been safely used in the clinic for the treatment of psychiatric disorders for many years." (PMID 33557839, 2021). "Specifically, GSK3B that codes for glycogen synthase kinase 3β plays a central role in the pathogenesis of psychiatric disorders." (PMID 33193575, 2020). "LiCl, a GSK3β inhibitor, has been used in the clinic for the treatment of psychiatric disorders for several decades." (PMID 30845991, 2019). "Collectively, these data demonstrate the importance of GSK3β/β-catenin as a potential pathway involved in the etiology of psychiatric disorders." (PMID 29449801, 2018). "In the present review, we will focus on the emerging roles of TRAX and its interacting proteins (including DISC1 and GSK3β) in psychiatric disorders and the potential implications for developing therapeutic interventions." (PMID 30285728, 2018). "Increasing evidence suggests that glycogen synthase kinase-3β (GSK-3β) plays a crucial role in neurodegenerative/psychiatric disorders, while pan-neural knockout of GSK-3β also shows detrimental effects." (PMID 28720858, 2017). "It is therefore important to understand the factors regulating GSK3β activity in the perspective of adapting therapy for several neurological and psychiatric disorders in which a dysregulation of GSK3β activity has been reported." (PMID 28203201, 2017). "Lithium is a well-established drug against psychiatric disorders that inhibits, amongst other targets, GSK3β." (PMID 25387847, 2014). "Much attention has been focused on GSK3β signaling in the brain due to its involvement in neurologic and psychiatric diseases." (PMID 20111716, 2010). "Similarly, lithium-based drugs, such as lithium citrate and lithium carbonate, which target GSK3β, hold potential due to their long-standing approval for psychiatric disorders and relatively low toxicity." (PMID 40074445, 2025).
psychiatric disorder (continued). "Pathogenic differences in phosphorylation of S268 and S270 would be expected to result in similar phenotypes to a genetic phospho-null model, and indeed the kinases that target these sites (ERK1/2 and GSK3β) show altered signaling in models of psychiatric disorders." (PMID 38503929, 2024). "The active form of Gsk3-β has been strongly related with psychiatric diseases." (PMID 25679528, 2015). "In line with this, systemic inhibition of GSK3β has been shown to have effects similar to those of mood stabilizers, antipsychotics or antidepressants in several behavioural tests used to model endophenotypes of psychiatric disorders in rodents." (PMID 22826345, 2012). "A lot of CREB target genes have been demonstrated to be closely related to psychiatric disorders, such as BDNF, protein kinase B (Akt), and glycogen synthase kinase 3β (GSK3β)." (PMID 38372284, 2024). "GSK3B, BDNF, NGF, NRG1, HTR2C, and PIP4K2A play important roles in molecular mechanisms of psychiatric disorders." (PMID 33193575, 2020). "Lithium is a standard inhibitor of GSK3β and has been an FDA approved mood stabilizer for the first line treatment of psychiatric disorders for over 50 years." (PMID 31349118, 2019). "Akt can exert its utility in controlling cellular proliferation by activating the phosphorylation of its downstream targets, GSK-3β, mTOR, and p70S6K, where GSK-3β is a pro-apoptotic protein whose activity plays an important role in neuropathology and psychiatric disorders." (PMID 39057075, 2024). "GSK3B, BDNF, NGF, NRG1, HTR2C, and PIP4K2A are genes that showed some importance in the study of the molecular etiology of psychiatric disorders." (PMID 33193575, 2020).
kidney disease (24 papers, 2012 to 2025). "In fact, the majority of research on GSK3β inhibitors in the context of kidney disease is still in the preclinical phase, relying on animal models and in vitro experiments." (PMID 40526103, 2025). "In renal diseases, particularly with aging, GSK-3β expression and activity are significantly upregulated in podocytes, and this aberrant activity is closely associated with the aging process." (PMID 40468463, 2025). "Some studies have used a lower dose of lithium chloride (30–80 mg/kg), by intraperitoneal injection, as an inhibitor of GSK-3β to treat renal diseases in LPS-induced or gentamicin-induced AKI model mouse models." (PMID 31002704, 2019). "Recent reports showed that the PI3K/AKT/GSK-3β pathway has been reported involved in cell proliferation, apoptosis, and inflammation in various kidney diseases." (PMID 31551783, 2019). "In patients with kidney disease, glucose uptake via GLUT1 is diminished via upregulation of glycogen synthase kinase 3 beta (GSK3β), which leads to systemic C. albicans infections and impairs survival." (PMID 38450755, 2024). "This review highlights the need for continued research to elucidate the precise functions of GSK3β within renal pathophysiology and to develop effective, targeted therapies that may improve outcomes for patients suffering from CKD and related renal diseases." (PMID 40526103, 2025). "SAA has also been reported to attenuate injury of kidney disease, which can be attributed to anti-inflammatory and anti-xidative activities by inhibiting the NF-κB and p38 MAPK signaling pathways and activating the Akt/GSK-3β/Nrf2 signaling pathway." (PMID 35910849, 2022). "We show here that in contrast to previous research indicating that podocyte‐specific genetic knockout of GSK3β has a beneficial effect in models of kidney disease; podocyte ablation of GSK3α is not similarly protective." (PMID 31825015, 2019). "However, there remains a significant lack of clinical studies evaluating GSK3β inhibitors for renal diseases." (PMID 40526103, 2025).